CD4 (CD4 molecule)
Diseases named in the same sentence as CD4 in open-access papers (continued):
Sharing a sentence is not in itself a finding about the gene and the disease.
HIV-1 infection (continued). "Activation of immune cells promotes specific mIFNLR1 expression and the direct interaction of IFN-λ3 with CD4+ T cells induces an antiviral state to decrease HIV-1 infection." (PMID 32353085, 2020). "One of the hallmarks of HIV-1 infection is chronic activation of the immune system that not only increases the number of activated CD4+ target cells but also directly impairs the immune system through activation-induced cellular exhaustion." (PMID 32886726, 2020). "Patients with chronic HIV-1 infections have been reported to have increased levels of soluble NKG2DLs in their sera, and HIV-1 infection of CD4+ T cells in vitro lead to increased MICA, MICB and ULBP2 surface expression but also increased protein shedding." (PMID 33352921, 2020). "Cell-cell fusion between HIV-1-infected CD4+ T cells and uninfected CD4+ T cells has been initially proposed to be another mechanism for HIV-1 infection and dissemination between T cells." (PMID 33348900, 2020). "Third, studying the effects of LY6E on HIV-1 infection of CD4 low-expressing cells, such as Jurkat T cells and primary monocyte-derived macrophages, revealed that HIV-1 entry was inhibited by LY6E." (PMID 32641482, 2020). "In this study, we investigated the molecular details of PSGL-1 restriction of HIV-1 infection of human CD4 T cells." (PMID 32273392, 2020). "It has been reported that the first two domains of CD4, D1D2, mimic the binding of CD4 receptor to gp120 and inhibit HIV-1 infection." (PMID 33569006, 2020). "Genes uniquely induced by IFNβ in gut CD4 T cells ex vivo were downregulated in the gut during chronic HIV-1 infection." (PMID 33064743, 2020). "In this study, we report another hnRNP member, RBMX, as a novel viral restriction factor that suppresses HIV-1 infection of CD4+ T cells by modulating HIV-1 5′-LTR-driven transcription." (PMID 32317327, 2020). "To identify the exact process during HIV-1 infection affected by MxB, we stably expressed MxB in human HeLa cells, primary macrophages and primary CD4+ T cells, tested the ability of these cells to restrict HIV-1." (PMID 32600399, 2020). "Briefly, CD4+ T cells increase glycolysis activity in response to HIV-1 infection and this metabolic reprogramming reciprocally facilitates virus invasion, latency formation, and inflammation." (PMID 33117366, 2020). "SAMHD1 was first identified as a restriction factor that blocks HIV-1 infection in myeloid and dendritic cells and was later linked to HIV-1 restriction in resting CD4-positive T cells." (PMID 33322320, 2020). "Candida specific-CD4+ T cells are preferentially lost at early HIV-1 infection with ongoing CD4 depletion." (PMID 31910871, 2020). "As CD161+ CD4+ T cells are memory cells, expressing high levels of CCR5, CCR6, and integrin α4, a phenotype associated with susceptibility to HIV-1 infection, we studied how these cells are affected during untreated AHI." (PMID 33322496, 2020). "Secondly, there is evidence that HIV-1 infection of CD4+ T cells induces upregulation of PVR expression and that the latent HIV reservoir is to some extent concentrated in CD4+ T cells expressing PVR and/or TIGIT." (PMID 32432050, 2020). "Next, correlation analyses were carried out between CD300a expression and clinical markers of HIV-1 infection such as CD4+ T cell count and viral load." (PMID 32269232, 2020). "Analysis of proviral composition under ART started during chronic HIV-1 infection has revealed similar levels of intact provirus and degrees of inducibility across resting memory CD4+ T cell subsets." (PMID 33087463, 2020). "Yu and colleagues elegantly demonstrated recently that LY6E enhances HIV-1 infection of CD4+ T cells and monocytic THP1 cells by promoting the expansion of viral fusion pores induced by HIV-1 Env." (PMID 32641482, 2020).
HIV-1 infection (continued). "Although the main targets for HIV-1 infection are CD4+ T-cells, considerable evidence suggests that HIV-1 also infects tissue macrophages, which can give rise to a long-lived reservoir under antiretroviral therapy (ART)." (PMID 33086748, 2020). "Although we have shown that apocynin at 1 mM completely abrogated CECs-mediated enhanced HIV-1 infection/replication in CD4+ T cells in the cord blood, it partially reversed the immunosuppressive properties of neonatal CECs even when 2 mM apocynin was used." (PMID 33329589, 2020). "SAMHD1 restricts HIV-1 infection in DCs, myeloid cells and resting CD4+ T cells by blocking reverse transcription due to limiting the dNTP pool - thus HIV-1 infection is prevented and efficient antiviral DC activation avoided." (PMID 33224139, 2020). "A previous study demonstrated that in vitro HIV-1 infection directly infects and selectively depletes CD4+ iNKT cells." (PMID 31190065, 2020). "CD4+ EV effects suggest that CD4+ T-cells utilize exosomes to protect against HIV-1 infection, indicating a role for EVs in antiviral immunity." (PMID 33096825, 2020). "Using an RNA-seq approach, we show that several members of the ERV9 lineage, particularly LTR12C elements, are activated upon HIV-1 infection of primary CD4+ T cells." (PMID 33021676, 2020). "Up to 40% of newly diagnosed cases of HIV-1 infection are late diagnoses, with a profound decrease in CD4 cell counts in many cases." (PMID 32076107, 2020). "More recently, two elegant studies showed that intron-containing RNA transcribed from the HIV-1 provirus activates innate immune signaling in MDDCs, macrophages, and CD4+ T cells in response to HIV-1 infection." (PMID 31968566, 2020). "BLT mice have been shown repeatedly to sustain mucosal HIV-1 infection and CD4+ T cell reconstitution in the FRT." (PMID 33746940, 2020). "In contrast, cytomegalovirus (CMV) specific CD4+ T cells are preserved in function, quantity and proliferation capacity during HIV-1 infection." (PMID 31910871, 2020). "A role for BIN-1 in HIV-1 infection is supported further by a study that identifies the upregulation of BIN-1 in CD4+ and CD8+ T cells from ex vivo patients." (PMID 32075937, 2020). "Since Meth was found to induce IL-1β and miR-146a expression, and these play important roles in immune regulation, we explored their effects on HIV-1 infection of CD4+ T-cells." (PMID 32117283, 2020). "Instead, LY6E was reported to promote the infection of enveloped RNA viruses from several viral families and modulates HIV-1 infection in a manner dependent on the level of CD4 expression in target cells." (PMID 32641482, 2020). "Resveratrol and pterostilbene completely blocked HIV-1 infection in resting CD4 T cells in the reverse transcription step at low molar concentrations." (PMID 33171952, 2020). "Disruption of CCR5 expression by lentiviral vector-mediated CRISPR/SaCas9 led to increased resistance against HIV-1 infection in human primary CD4+ T cells." (PMID 31186067, 2019). "Human papilloma virus specific CD4+ T-lymphocytes have also been shown to be lost early after HIV-1 infection." (PMID 31487324, 2019). "HIV-1 infection is characterized by a complex immune disorder that presents itself as a decrease in CD4+ T cells, chronic immune activation, and imbalanced cytokine and chemokine production and macrophage dysfunction." (PMID 30979916, 2019). "HIV-1 infection therefore limits the transition of CD4+ T cells from an effector to long-lived memory state." (PMID 31507594, 2019). "HIV-1 infection is characterized by depletion of CD4+ T cells and an inversion of the CD4/CD8 T cell ratio." (PMID 31319498, 2019). "Eligible participants were 13 years of age or older, had HIV-1 infection with a CD4 count of less than 250 (the CD4 count threshold for HIV treatment eligibility at the time), had not previously received ART, and had confirmed or probable TB." (PMID 30707696, 2019).
HIV-1 infection (continued). "In agreement, we found enhanced HIV-1 infection in CD4+ T cells when cocultured with autologous CECs in vitro." (PMID 31772057, 2019). "Monocytes/macrophages express the CD4 receptor, although at lower levels compared to CD4+ T cells and, therefore, are permissive to HIV-1 infection." (PMID 30889861, 2019). "Untreated HIV-1 infection is characterized by a progressive depletion of memory CD4+ T cells which mostly express CD127, the α chain of the IL-7 receptor (IL-7R)." (PMID 31507594, 2019). "As we will explain in the next sections, internalized virus can be processed and presented in the cell surface for T cell priming, or can on the contrary be transferred to CD4+ T cells, promoting this way the HIV-1 infection and spread." (PMID 31708924, 2019). "EVs produced during other viral infections such HIV-1 have ambiguous roles depending of the type of EVs and the cell type producing those vesicles; for example, EVs released by CD4+ T cells mediate the CD4-dependent inhibition of HIV-1 infection in vitro." (PMID 31547130, 2019). "In summary, NSG mice engrafted with human CD4+ cells transduced with NB-ZSG prior to HIV-1 infection had undetectable viral RNA in plasma, whereas high levels of viral RNA were detected in the plasma samples of control mice." (PMID 31455650, 2019). "Third, during chronic HIV-1 infection, the production of IFN persists, causing apoptosis of T cells and contributing to decrease in CD4+ cell count." (PMID 31708924, 2019). "First, it will be necessary to demonstrate that a sufficiently high proportion of primary CD4+ T cells, the target of HIV-1 infection, can be engineered to express A3G-D128K to effectively inhibit HIV-1 replication and spread." (PMID 31778955, 2019). "CD4+ T cell decline during HIV-1 infection has been shown to be more accurately predicted by levels of chronic immune activation than viral load, underlining the importance of both host and virus in pathogenesis." (PMID 31449552, 2019). "In this paper, the fractional-order differential model of HIV-1 infection of CD4+ T-cells with the effect of drug therapy has been introduced." (PMID 30728851, 2019). "Somewhat surprisingly, we recently uncovered a new yet distinct effect of LY6E on HIV-1 infection in low CD4-expressing T cells." (PMID 31684192, 2019). "Exosomes derived from CD4+T cells that contain CD4 inhibit HIV-1 infection compared to CD4-depleted exosomes." (PMID 30702421, 2019). "We monitored the counts of CD4+ T cells in each group at different time points to assess the effect of HIV-1 infection in cells modified with CRISPR/SaCas9-sgRNA-#8 in vivo." (PMID 31186067, 2019). "The duration of HIV-1 infection was calculated using baseline CD4+ T-cell (CD4) counts determined at enrollment." (PMID 30866830, 2019). "Intriguingly, the effects of METH on HIV-1 replication in human CD4+ T-cells that are the primary targets of HIV-1 infection and replication in vivo remain largely unclear." (PMID 30779732, 2019). "NB-ZSG and ZSG were delivered by using a retroviral vector where CD4+ cells were transduced either prior to (preinfection) or following (postinfection) HIV-1 infection." (PMID 31455650, 2019). "We enrolled 9 asymptomatic adult volunteers with a newly diagnosed HIV-1 infection and CD4 T cell counts ≥ 350/ml." (PMID 31492170, 2019). "Due to the quiescent nature, HIV-1 infection of naïve CD4+ T-cells is highly inefficient, and rarely proceeds to proviral integration into the host cell genome." (PMID 31487807, 2019). "We show here that HIV-1 infection leads to the upregulation of miR-146b-5p in CD4 T cell-derived EVs from ART-naive HIV-1-infected patients." (PMID 31311940, 2019). "In another case, recombination in gp120 entailed the coreceptor switch to CXCR4, despite the recent acquisition of HIV-1 infection in 2012 confirmed by CD4+ T-cell count and viral load measure at diagnosis." (PMID 31031735, 2019).
HIV-1 infection (continued). "Therefore, CD32 expression in CD4+ TRM could identify a subset remarkably susceptible to HIV-1 infection, potentially highly activated within an overall more quiescent TRM compartment, which may or may not continue to express this marker throughout the different stages of the retroviral infection." (PMID 31628331, 2019). "Critically, and similar to HIV-1 infection in humans, in this model, HIV-1 infection resulted in an overall reduction of total CD4 T cell counts in peripheral blood and spleen." (PMID 30867315, 2019). "CECs from HIV patients and human cord blood/placenta exacerbate HIV-1 infection/replication when cocultured with CD4+ T cells, and that preexposure of CD4+ T cells to CECs enhances their permissibility to HIV infection." (PMID 31772057, 2019). "CD3+ CD4+ T helper cells, the main target for HIV-1 infection, as well as CD3+ CD8+ cytotoxic T cells were present at physiological frequencies, and despite their lower repopulation, both CD11b+ macrophages and CD14+ monocytes were present in all major organs." (PMID 30867315, 2019). "CD4+ T cells from PRs were able to support cis HIV-1 infection before ART, but to a significantly lesser degree after ART initiation." (PMID 31304185, 2019). "Acute HIV-1 infection is characterized by a compartmentalized CD4+ T cell depletion and constant viral replication, counteracted by a broad antiviral effect of the innate immune response." (PMID 31582776, 2019). "Human immunodeficiency virus type-1 (HIV-1) infection is triggered by its envelope (Env) glycoprotein gp120 binding to the host-cell receptor CD4." (PMID 30634692, 2019). "HIV-1 infection results in systemic CD4+ T cell depletion, thereby impairing cell-mediated immunity." (PMID 30682089, 2019). "These recombinant protein chimeras have been expressed on the surface of T cell lines and primary CD4+ T cells, conferring particularly potent, broad and durable protection from HIV-1 infection to primary CD4+ T cells in vitro and in humanized mice." (PMID 30824796, 2019). "Our work reveals a novel role for CEC-mediated enhanced HIV-1 infection/replication in CD4+ T cells." (PMID 31772057, 2019). "Further experiments revealed that the differential phenotype of LY6E on HIV-1 infection is dependent on the level of CD4 in target cells." (PMID 31684192, 2019). "For example, cathepsin B inhibition by cystatin C or CA-074Me (synthetic inhibitor) treatment resulted in enhancement of the CD4-independent HIV-1 infection in HeLa and TE671 cells." (PMID 31077130, 2019). "Individuals were more likely to present for clinical care at the chronic stage of HIV-1 infection with a median CD4 count of 325 cells/μL." (PMID 31754119, 2019). "A 47-year-old homosexual male with HIV-1 infection, on antiretroviral therapy (last CD4 cell count 1022 cells/μL) presented to our emergency department with a five-day history of headache, blurry vision, pain and redness of the left eye." (PMID 31011497, 2019). "Preexposure of CD4+ T cells to autologous cord blood CECs enhance their infectivity to HIV-1 infection." (PMID 31772057, 2019). "CEC-mediated enhanced HIV-1 infection in CD4+ T cells was dose dependent for both X4-tropic and R5-tropic viral isolates, respectively." (PMID 31772057, 2019). "During mucosal exposure, HIV-1 infection often occurs via transfer of virus from dendritic cells (DCs) to monocytes/macrophages, while direct infection of CD4+ T cells is more likely during parenteral transmission." (PMID 30702421, 2019). "For instance, resting CD4+CD25+ Treg were found to be sensitive to HIV-1 infection acting as a viral reservoir in patients under long ART." (PMID 32038533, 2019). "In CD4+ T cells, the expression APOBEC3G increases with activation, but it translocated to the nucleus, which is compatible with the increase in HIV-1 infection susceptibility." (PMID 31708924, 2019).
HIV-1 infection (continued). "To investigate the effect of IFN-I stimulus on gene expressions in the intrinsic target cells for HIV-1 infection, including CD4+ T cells, monocytes, and MDMs, we analyzed publicly available transcriptome data of these cells treated with IFN-I." (PMID 30915053, 2019). "Our findings also point to a potential use of neutralizing anti-interferon α/β receptor antibodies to rescue the defective memory CD4 T-cell survival during HIV-1 infection, even in HIV-1 specific CD4 T-cell." (PMID 31658294, 2019). "This is evident in CD4+ cells that expressed high levels of NB-ZSG prior to HIV-1 infection and were highly resistant to HIV-1 replication, as indicated by strongly reduced levels of HIV-1 mRNA in the cells." (PMID 31455650, 2019). "HIV-1 infection of CD4+ T cells and macrophages have been shown to induce an anti-apoptotic gene profile and resistance to apoptosis." (PMID 31866988, 2019). "It is well-established that CD4 T-cell activation is a key factor in facilitating HIV-1 infection and cell depletion." (PMID 31658294, 2019). "Dysregulated IL-7/IL-7R signaling in HIV-1 infection has been proposed by several groups as a critical link between HIV-1-driven immune activation and bystander CD4+ T cell loss." (PMID 31507594, 2019). "Unlike naïve CD4+ T-cells, which are quiescent in nature and are unable to support productive infection, and the same as for efficient HIV-1 infection, metabolically active CD4+ T cells are required." (PMID 31487807, 2019). "The results indicate that NB-ZSG expression in CD4+ cells prior to HIV-1 infection resulted in undetectable HIV-1 RNA in animal plasma for up to 31 dpi." (PMID 31455650, 2019). "We demonstrated a decreased frequency of CD4+CD56+ T cells but increased frequency of CD8+CD56+ T cells in HIV-1 infection." (PMID 31379845, 2019). "We observed that CD161+ CD4+ T cells were highly permissive to X4- or R5-tropic HIV-1 infection and harbored total HIV-1 DNA at significantly higher frequencies than the CD161-negative population." (PMID 31594817, 2019). "Productive infection of DCs is a rather rare event, 10- to 100-fold less frequent in vivo than CD4+ T cell HIV-1 infection." (PMID 31708924, 2019). "In acute HIV-1 infection the viral load rapidly increases alongside a burst of cytokines such as IFN-α and overstimulated pro-apoptotic CD4+ T cells; the immunological hallmark of HIV-1 infection." (PMID 31921122, 2019). "SAMHD1, a dNTP triphosphohydrolase, restricts productive HIV-1 infection in dendritic cells, myeloid cells and resting CD4+ T cells." (PMID 31220191, 2019). "We investigated the dynamic host response to HIV-1 infection by systematically measuring transcriptomic, proteomic, and phosphoproteomic expression changes in infected and uninfected SupT1 CD4+ T cells at five time points of the viral replication process." (PMID 30659199, 2019). "CD40L that expressed predominantly on activated CD4+ T-cells and play multiple role in HIV-1 infection." (PMID 31521107, 2019). "CD4+ T-cell, macrophage, and dendritic cells are vulnerable to human immunodeficiency virus type 1 (HIV-1) infection because of their CD4 receptor that the HIV-1 virus uses to infect those cells." (PMID 31521107, 2019). "Here, we showed that CRISPR/SaCas9 combined with a sgRNA to target the CCR5 in human primary CD4+ T cells inhibited HIV-1 infection." (PMID 31186067, 2019). "Decreased levels of CD4 render potential host cells refractory to HIV-1 infection and presumably HIV-2, HHV6, and any other viruses that use CD4 as a receptor." (PMID 31559009, 2019). "Despite these differences to in vivo physiology, this new ex vivo 3D culture system recapitulated the motility speeds of CD4 T lymphocytes and their reduction upon HIV-1 infection observed in humanized mice." (PMID 31086185, 2019). "In contrast, Apo, which is the NADPH-dependent ROS inhibitor, abrogated the enhanced HIV-1 infection/replication in CD4+ T cells by CECs." (PMID 31772057, 2019).